ALB (albumin)
Diseases named in the same sentence as ALB in open-access papers (continued):
Sharing a sentence is not in itself a finding about the gene and the disease.
malnutrition (continued). "Research has also demonstrated a correlation between indications of malnutrition, especially reduced serum albumin levels, and elevated morbidity and mortality rates." (PMID 37742012, 2023). "The number of patients meeting the definition of malnutrition according to BMI (< 18.5 kg/m2) and serum albumin (< 3.5 g/dL) was 58 (0.7%) and 1,039 (13.2%), respectively." (PMID 36512458, 2023). "Conversely, increased levels of CRP and its end products, tumor necrosis factor-alpha (TNF-α) and interleukin-6 (IL-6), lead to decreased levels of the malnutrition marker albumin." (PMID 37760482, 2023). "There were seven single measures used to define malnutrition: albumin, arm muscle circumference, BMI, cholinesterase, haemoglobin, neutrophil to lymphocyte ratio, and the total number of lymphocytes." (PMID 37749757, 2023). "Haemoglobin (Hb) and serum albumin have been extensively investigated as biomarkers of malnutrition in cancer patients." (PMID 37906352, 2023). "Malnutrition is typically defined as the presence of a low body mass index (BMI) and low serum albumin levels." (PMID 37599357, 2023). "A decrease in albumin levels is a significant indicator of malnutrition and contributes to changes in PhA." (PMID 38068848, 2023). "People with a lower phase angle had a higher risk of malnutrition (MNA), as well as the results obtained on the NRI scale or the level of albumin concentrations." (PMID 37447196, 2023). "Since blood albumin estimation is quick and the test is widely accessible, serum albumin is a more accurate indicator of malnutrition than body mass index (BMI)." (PMID 37123772, 2023). "High AG and increased AG level can result in irreparable damage in elderly patients including increased muscle protein catabolism with muscle wasting, reduced albumin synthesis with malnutrition, promotion of systemic inflammation, increased bone resorption." (PMID 37027077, 2023). "This is calculated using serum albumin and is an objective indicator of malnutrition, but A is the most widely used and the easiest to study." (PMID 37009613, 2023). "They showed that albumin, hemoglobin, total cholesterol, and total serum protein, were useful biochemical markers of malnutrition." (PMID 37034317, 2023). "In non-diabetic patients with chronic kidney disease, a negative correlation between serum resistin concentration and albumin level as a marker of malnutrition was observed, which is consistent with the results of the presented study." (PMID 36978817, 2023). "The decrease in serum albumin reflects malnutrition and low immunity, which will increase the complications of the tumor and reduce the tolerance to treatment." (PMID 37077828, 2023). "Our study reveals that the average serum albumin level was significantly lower in those with more severe COVID-19 infection, and that hypoalbuminemia increased the odds of having malnutrition as assessed by GLIM." (PMID 37049600, 2023). "Malnutrition can undermine the body’s capacity to recover from injury, whereas inflammation can accelerate albumin breakdown." (PMID 37998586, 2023). "The serum albumin (2.63–2.73 g/dL) indicated moderate malnutrition due to the tortilla’s lower protein content." (PMID 37761036, 2023). "The presence/absence of PCF, weight, anemia status (Hb <12.5 g/dl), renal dysfunction status (GFR <90 mL/min/1.73m2), malnutrition status (Albumin <3.5 g/dl), and marginal involvement status was extracted from postoperative medical records." (PMID 37251293, 2023). "This chronic state of malnutrition contributes to a decline in albumin production, leading to hypoalbuminemia." (PMID 37622995, 2023). "Low albumin level indicates a malnutrition status and often occurs in patients with oral cancer because food intake ability is impaired." (PMID 36897190, 2023). "The high prevalence of malnutrition was found in patients with BMI <18.5 kg/m2 (94.12%), and patients with albumin<35 g/L (74.68%)." (PMID 36960208, 2023).
malnutrition (continued). "In the analyses of patient background factors, the malnutrition group showed a lower left ventricular ejection fraction, serum albumin level, and BMI." (PMID 36638132, 2023). "Conventionally, an ALB concentration < 3.5 g/dL, which widely known as hypoalbuminemia, is regarded as a standard indicator of malnutrition." (PMID 37715131, 2023). "Higher endocan levels were associated with lower nutrition assessments by subjective goal assessment, higher malnutrition-inflammation scores, and lower serum albumin levels." (PMID 38068479, 2023). "On the other hand, malnutrition a common finding among CKD patients is mostly diagnosed by serum albumin which is considered widely as a marker for nutritional status in CKD patients 52-53." (PMID 38357113, 2023). "For instance, malnutrition is often signaled by diminished serum cholesterol and albumin levels, as well as reduced lymphocyte counts." (PMID 38129842, 2023). "In this investigation, we focused on the geriatric nutritional risk index (GNRI), a comprehensive metric that takes into account the patient’s ideal weight, actual weight, and serum albumin levels to measure malnutrition." (PMID 38024341, 2023). "Serum albumin which is often used as a surrogate for malnutrition and/or illness severity was significantly lower in patients with delirium (32.9 ± 5.5 g/dl vs. 34.6 ± 4.9 g/dl)." (PMID 36683168, 2023). "As hypoalbuminemia is independently associated with both malnutrition and inflammation in patients with CD and was most profound in subjects with both malnutrition and active inflammation, these results suggest that low serum albumin may be a marker of either malnutrition or active disease." (PMID 38036713, 2023). "The role of inflammation as a risk factor for malnutrition in HD has been recognized in previous trials, and C-reactive protein (CRP) levels have been correlated with the inhibition of albumin synthesis in this particular population." (PMID 37512123, 2023). "Analysis of different quick parameters of malnutrition in one study has revealed that Body Mass Index (BMI) and serum albumin have high predictive values in IBD patients with active disease." (PMID 38036713, 2023). "Of the 82 patients, 76 (92.7%) were suspected of having malnutrition according to their serum albumin levels, 67 (81.7%) were defined as being at risk of malnutrition per the GNRI, and 32 (39.0%) were defined as being at risk of malnutrition per the NRI." (PMID 36595498, 2023). "Low albumin levels and malnutrition can lead to increased systemic inflammation and vascular sclerosis, and proper dietary supplementation can effectively prevent disease progression and worse outcomes." (PMID 37559005, 2023). "Age ≥ 65 years, hs-CRP ≥ 1 mg/L, low ALB, low HB, low BMI, and BWL > 2.4% were independent risk factors for malnutrition in GC patients." (PMID 37293590, 2023). "In peritoneal dialysis, a high endocan level has been reported to be negatively correlated with nutrient status, including albumin level, subjective global assessment, and malnutrition inflammation score." (PMID 38068479, 2023). "Albumin and prealbumin are the proteins most widely studied for diagnosis of malnutrition, being useful indicators for general nutritional status." (PMID 37239661, 2023). "In this study, albumin is preferred because it is a good predictor of malnutrition and has been proven to be an early detection marker for postoperative complications." (PMID 37601530, 2023). "The number of patients with malnutrition defined as albumin levels below the normal reference value) is significantly higher in the TALL 250-cm group (40.5%) versus both the TALL 300-cm group (14.3%) and the pre-distalization group (15.6%)." (PMID 36459358, 2023). "If a patient’s albumin level is low, it indicates malnutrition, which can be accompanied by tissue edema and decreased resistance, increasing the risk of postoperative complications." (PMID 37637824, 2023).
malnutrition (continued). "There are several established methods for stratifying malnutrition in PD, with one commonly used marker being serum albumin." (PMID 38021540, 2023). "Reduced serum albumin levels represent the state of malnutrition and reflect the body's ongoing systemic inflammatory response." (PMID 37165423, 2023). "The CONUT score, which is calculated using the serum albumin level and lymphocytes, is an efficient and simple tool for detecting malnutrition." (PMID 37795077, 2023). "In the current study, mean level of serum albumin was low in patients with malnutrition (3.03 ± 0.58 g/dl) as compared to well-nourished (3.71 ± 0.58 g/dl) adult patients with cancer, and the difference was statistically significant." (PMID 36869395, 2023). "This phenotype is characterised by low body weight, increased prevalence of malnutrition markers such as low serum albumin, low serum cholesterol, low Hb, low HbA1c, and increased risk of hypoglycaemia." (PMID 37367862, 2023). "The Nutrition Risk Index (NRI) is a diagnostic tool designed to predict surgical outcomes with correlation to malnutrition using the serum albumin level and comparing a patient’s actual weight with the usual one." (PMID 37836461, 2023). "The findings also revealed a statistically significant correlation between ALB and malnutrition (P < 0.001), suggesting that patients with higher ALB presented lower probability of malnutrition." (PMID 37715131, 2023). "The authors of this study concluded that the albumin concentration, along with BMI, were the best predictors of malnutrition in IBD patients." (PMID 37571416, 2023). "Patients with anemia were more often malnourished or at risk of malnutrition according to MNA-SF (p = 0.047), with lower serum albumin concentration (p < 0.001), which is consistent with our observations." (PMID 37447196, 2023). "As discussed by Hickson, for the assessment of malnutrition, particular attention should be paid to albumin, prealbumin, haemoglobin, total cholesterol, and total protein." (PMID 37111024, 2023). "In cancer and cancer-related malnutrition, high production of cytokines such as TNF-α, IL (interleukin) -2, and IL-6 cause metabolic disruption which inhibits albumin gene expression and causes vascular permeability." (PMID 36869395, 2023). "Among proteins, albumin and transferrin, for example, play an important role in the assessment of malnutrition." (PMID 37111024, 2023). "Albumin is also a crucial traditional laboratory marker for estimating malnutrition at the clinical level." (PMID 37867496, 2023). "Similar results were found in the sensitivity analyses conducted using serum albumin levels to define malnutrition." (PMID 37479734, 2023). "The reduced TG, ALB, TG and GLU were attributable to the nutritional deficiency secondary to food intake reduction." (PMID 37601058, 2023). "The degree of malnutrition in CKD patients was significant negatively correlated with the expression levels of ALB (r = −0.188), PA (r = −0.262) and Hb (r = −0.176) (P < 0.05)." (PMID 36687720, 2022). "Both serum albumin and hemoglobin have been reported to be biomarkers of malnutrition in older people." (PMID 35313647, 2022). "Currently, there are some other tools developed for assessing malnutrition; the trend of introducing novel tools is based on the minimal use of visceral proteins, such as albumin." (PMID 35800664, 2022). "Here, we explored the roles of albumin and albumin-independent mechanisms in oedema formation among children with severe malnutrition (SM)." (PMID 35398787, 2022). "Albumin is one of the factors used to measure the liver synthesis rate, but it is also affected by malnutrition." (PMID 36292245, 2022). "Low plasma albumin (hypoalbuminemia), a protein produced and secreted by the liver, is a sign of severe malnutrition and is indicative of liver synthetic function." (PMID 36402829, 2022).
malnutrition (continued). "While albumin is one of the important indicators of malnutrition, it is also closely related to immune incompetence and leads to accelerated tumor progression through the suppression of tumor immunity." (PMID 36242047, 2022). "Albumin is regarded as one of the major components of human plasma, and malnutrition is usually defined as an albumin level under 3.5 mg/dl." (PMID 36514037, 2022). "Persistent inflammation contributes to decreased ALB levels, plays a central role in the malnutrition, inflammation, which predicts poor clinical outcomes." (PMID 35967813, 2022). "Malnutrition and inflammation suppress albumin synthesis, thereby reducing immune defense, impeding treatment response, and contributing to adverse outcomes in patients with cancer." (PMID 36587139, 2022). "Malnutrition in the elderly can become evident via serum proteins such as: (a) pre-albumin, (b) albumin, (c) transferrin, and (d) retinol-binding protein (RBP)." (PMID 35892736, 2022). "Increased malnutrition risk was linked with higher age and BUN and lower albumin and hematocrit levels." (PMID 36320896, 2022). "The patients of the IN Group showed instead malnutrition (Albumin: 30.5 ± 6.5 vs 37.6 ± 6 g/L; p = 0.03) and pro-inflammatory state (NLR: 7.1 ± 6.7 vs 3.8 ± 2.4; p = 0.05) (PLR: 312 ± 203 vs 194 ± 99; p = 0.04) greater than the HM Group." (PMID 36100879, 2022). "Other altered biochemical indicators reflecting malnutrition and its deleterious cellular effect are low hemoglobin, absolute lymphocyte, and albumin levels in blood patients with low PA, as recently described by the Leon-Idougurram group." (PMID 35893884, 2022). "The baseline hemoglobin, total cholesterol, total lymphocyte count and albumin level were significantly lower in the group with malnutrition." (PMID 36466405, 2022). "The benefits of preoperatively identifying serum albumin include its cost and a potential opportunity to preoperative correct malnutrition, which has been proven to improve the postoperative results." (PMID 35831810, 2022). "In a laboratory test, malnutrition is defined as follows: albumin concentrations <3.5 mg/dl, total lymphocyte count <1,500/mm3, or serum transferrin concentrations <200 mg/dl." (PMID 36684164, 2022). "Albumin is a prognostic measure for protein-calorie malnutrition; therefore, it is monitored before and after bariatric surgery." (PMID 35807778, 2022). "Patients with a longer ICU stay were related to malnutrition and reduced baseline albumin levels, which decreased the therapeutic effect." (PMID 36337861, 2022). "Elevated albumin levels occur with dehydration and shock, while malnutrition and gastrointestinal disease can decrease the levels among other circumstances." (PMID 36303601, 2022). "Other indicators of malnutrition such as low albumin or low protein level were higher among older people who developed delirium compared to them without but without reaching statistical significance." (PMID 36011202, 2022). "In the retrospective phase, the most common inappropriate albumin indications were hypoalbuminemia and malnutrition." (PMID 35370698, 2022). "High levels of PAR represent higher platelet counts with inflammatory response, and lower levels of albumin with malnutrition, eventually resulting in inferior short-term clinical outcomes of critically ill patients with CRC." (PMID 35664562, 2022). "mSIS is a score based on albumin levels, that are known to be elevated in states of systemic inflammation and malnutrition, in combination with LMR." (PMID 35733396, 2022). "At the same time, the increase in systemic inflammation of patients with low albumin levels and malnutrition promotes atherosclerosis, also known." (PMID 35902808, 2022). "Meta-analysis of over 50,000 participants showed that total protein and albumin were reliable indicators of malnutrition." (PMID 35805838, 2022).
malnutrition (continued). "A study by Chien proved that malnutrition defined as decreased albumin concentrations was related with remodeling of the left ventricle and LVDD." (PMID 36364925, 2022). "Well-nourished or moderately malnourished patients had a higher albumin concentration compared to patients with moderate or severe malnutrition (median: 3.40 vs. 3.22 g/L; p = 0.0118)." (PMID 35884467, 2022). "In contrast, serum albumin levels are a parameter of malnutrition and decrease during a systemic state of inflammation through increased CRP synthesis." (PMID 35327399, 2022). "Both malnutrition and inflammation reduce serum albumin level by decreasing synthesis and accelerating degradation." (PMID 36346823, 2022). "Malnutrition is common in patients with cancer, particularly in patients with locally advanced or metastatic malignancies, and albumin levels are generally significantly lower than those prior to the occurrence of cancer before due to excessive metabolism." (PMID 36684183, 2022). "The patients of intramedullary group showed malnutrition (Albumin: 30.5 ± 6.5 vs 37.6 ± 6 g/L; p = 0.03) and pro-inflammatory state (NLR: 7.1 ± 6.7 vs 3.8 ± 2.4; p = 0.05) (PLR: 312 ± 203 vs 194 ± 99; p = 0.04) greater than megaprostheses group." (PMID 36100879, 2022). "Compared with albumin, serum pre-albumin is considered a more sensitive indicator of nutritional status, which has also been used as a blood marker for malnutrition." (PMID 36742004, 2022). "Serum albumin is a simple and valuable marker that can reflect malnutrition or cachexia in cancer patients." (PMID 36061883, 2022). "Group 1 was characterized by lower serum albumin, prealbumin, Cr, K, and BUN, lower nPCR and higher hs-CRP levels, implying that high APR is associated with malnutrition and subclinical inflammation." (PMID 36346823, 2022). "In fact, the controlling Nutritional Status (CONUT) score, a screening tool for evaluating malnutrition, takes into account serum albumin, total cholesterol, and total lymphocyte levels." (PMID 36289923, 2022). "This study also investigates the ability of serum albumin in early detection of the LMGB-induced malnutrition." (PMID 35800664, 2022). "As well, 10% have sign of malnutrition defined as a serum-albumin level of <3 g/dl and/or a BMI of <20 kg/m2." (PMID 37675001, 2022). "Given the possible malnutrition origin of low albumin and total protein level, accurate nutritional evaluation is recommended to establish the nature of these alterations." (PMID 36235705, 2022). "Serum albumin is a significant indicator of nutrition status in the elderly, and malnutrition characterized by low serum albumin was independently associated with increased adverse cardiovascular events and mortality." (PMID 35923200, 2022). "A decrease in serum albumin and prealbumin were the parameters that most accurately diagnosed malnutrition according to 74.1% of participants, whereas a body mass index (BMI) < 20 kg/m2 was selected by 8.6%." (PMID 36432451, 2022). "ALB was the majority of total serum protein and represented the nutritional condition of the participants, as hypoalbuminemia is related to malnutrition or other illness." (PMID 35447934, 2022). "Tumor depletion and inflammation often lead to decreased serum albumin levels in cancer patients, while malnutrition can suppress immune defense mechanisms and contribute to tumor progression." (PMID 35317078, 2022). "The GPS includes the value of albumin and CRP, which are associated with inflammation and malnutrition." (PMID 36540477, 2022). "Well-nourished patients had a higher albumin concentration compared to patients with moderate or severe malnutrition (median: 3.75 vs. 3.30 g/L; p < 0.0001)." (PMID 35884467, 2022). "Although the discriminatory capacity of serum albumin (S-albumin) in identifying malnutrition is limited, it is of note that optimization of the S-albumin level nevertheless contributes to a reduction in mortality during the first year of HD." (PMID 36296981, 2022).